SIRT2 (sirtuin 2)
Diseases named in the same sentence as SIRT2 in open-access papers (continued):
Sharing a sentence is not in itself a finding about the gene and the disease.
tumor (continued). "In NSCLC, deacetylation of PGAM-K100 by SIRT2 leads to increased NADPH generation and faster tumor growth." (PMID 39479446, 2024). "The expression of SIRT2 in CRPC leads to unchecked p300 activity, which drives transcriptional programs promoting tumor aggression and resistance to androgen receptor signaling inhibitors (ARSIs)." (PMID 39796040, 2024). "SIRT2 reverses the GCN5-induced acetylation of LIFR at K620, disrupting its homodimerization, PDPK1 activation, and AKT signaling, thereby attenuating tumor growth and positioning LIFR-K620 acetylation as a biomarker and therapeutic target in PCa." (PMID 39796040, 2024). "Sirtuins, such as SIRT1, SIRT2, and SIRT6, interact with crucial signaling pathways, influencing tumor metabolism, genomic stability, and the progression of ADM." (PMID 39682281, 2024). "The major findings include overall restricted tumor growth using a novel transgenic approach and new evidence that c-MYC’s stability and localization to the nucleus are mediated by Sirt2 deacetylation." (PMID 37628798, 2023). "Pharmacologic inhibition of Sirtuin-2 (Sirt2), a NAD+-dependent deacetylase inhibiting T-cell metabolism and impairing T-cell effector functions, endows human tumor-infiltrating lymphocytes (TILs) with superior metabolic fitness and effector functions." (PMID 37046597, 2023). "Studies have shown that the expression of SIRT2, SIRT3, SIRT6, and SIRT7 is increased in tumor-stage 1-4 subgroups, SIRT1 expression is increased in tumor-stage 1, and the expression of SIRT4 is decreased." (PMID 37096064, 2023). "Additionally, the NAD+-dependent deacetylase SIRT2 can also govern the metabolic fitness of immune cells by blocking the activities of key enzymes in multiple metabolic pathways, thus impairing effector functions of tumor-reactive T cells in the tumor microenvironment." (PMID 37165408, 2023). "Recently, the inhibition of sirtuin-2 (Sirt2) was proposed as a potential treatment for HCC, despite contradictory findings of its role as both a tumor promoter and suppressor in vitro." (PMID 37628798, 2023). "However, whether SIRT2 functions as an oncogene or a tumor suppressor has been heavily debated." (PMID 37916830, 2023). "Immunofluorescent staining revealed a higher level of SIRT2 proteins in NSCLC lung tumor tissues than normal tissues, which inversely correlated with a lower level of ITGB3‐aK416 in NSCLC tumor tissues than normal tissues." (PMID 36453571, 2023). "Interestingly, pharmacological inhibition of SIRT2 blocks the therapeutic action of NAD+ against NAFLD pathologies, while SIRT2 deficiency reprograms T-cell metabolism by targeting metabolic enzyme hyperacetylation, leading to a more effective antitumor immune response in the tumor microenvironment." (PMID 39871927, 2022). "In turn, genetic depletion and pharmacological inactivation of SIRT2 reversed stabilization of the SLUG transcription factor and inhibited tumor growth." (PMID 35406775, 2022). "SIRT2 deacetylation is an important mechanism that regulates IDH1, which can exhibit tumour suppressor function by targeting the IDH1 K224 residue." (PMID 36101744, 2022). "A recent study reported that SIRT2 can promote BRCA1-BARD1 heterodimerization via its deacetylase activity, which facilitates HR pathway and tumor suppression." (PMID 36060706, 2022). "The other members of the sirtuin family, SIRT2–7, similar to SIRT1, can also act as oncogenes or tumour suppressors according to the type of tumour." (PMID 36078035, 2022). "In OC, BRCA1 affects the migration of tumor cells by regulating CAPN1 and plays an important role in double-stranded DNA damage repair via its interaction with SIRT2." (PMID 35941978, 2022). "The decreased expression levels of SIRT2, SIRT4, and SIRT5 were correlated with advanced tumor stages." (PMID 35136826, 2022).
tumor (continued). "The expression levels of CCND1, VEGFA, AURKB, HDAC1, HSP90AA1, and HSP90AB1 were positively correlated with immune cell infiltration levels, whereas the expression levels of SIRT2 and CASP9 were negatively correlated with the tumor purity of BRCA." (PMID 35845599, 2022). "We performed histochemical staining of SIRT2 and Snail in the tumor tissues of nude mice subcutaneously injected with MG63-shSIRT2 or control cells, and showed that the Snail staining was weakened after SIRT2 knockdown." (PMID 36344502, 2022). "Thirdly, in tumor and normal tissues of LUAD and LUSC, the levels of SIRT2 expression showed different patterns of correlation with the regulation of various immune cells (eg, Th1, central memory T cells, and resident memory T cells)." (PMID 36844923, 2022). "Although both SIRT1 and SIRT2 were secreted into the extracellular space, only SIRT2 deacetylated LIFR‐K620 acetylation, indicating that the tumour microenvironment of PCa has certain characteristics and functions." (PMID 35172032, 2022). "Sirtuin 2 (SIRT2) is a NAD+-dependent deacetylase, which regulates multiple biological processes, including genome maintenance, aging, tumor suppression, and metabolism." (PMID 35264593, 2022). "Acetylation of ACLY stabilizes it by preventing ubiquitylation and degradation, and it stimulates de novo lipid synthesis and tumor cell proliferation, whereas deacetylation of ACLY by a deacetylase, such as SIRT2, destabilizes it." (PMID 36358687, 2022). "SIRT2 deacetylates and promotes KRAS activity, thereby inducing cell proliferation, colony formation, and tumor growth." (PMID 34650436, 2021). "Due to the toxicity and impermeable blood-brain barrier characteristics of AGK2, another SIRT2 inhibitor, AK7 was tested in GB2 tumor xenograft mice models." (PMID 34650436, 2021). "Another study using MDA-MB-231 cell (a BLBC cell line) demonstrated that SIRT2 silenced Arrestin domain-containing 3 (ARRDC3), a tumor suppressor, contributing to the aggressive nature of BLBC cells." (PMID 33014852, 2020). "Compared to normal liver tissues, SIRT1 (p = 0.002), SIRT2 (p = 0.01), and SIRT4 (p = 0.045) were significantly up-regulated in tumor tissues." (PMID 33093847, 2020). "And clinical analysis revealed that the impact of SIRT2 on breast cancer depends on the tumor grade, for example, SIRT 2 acts as a tumor suppressor in Grade 2 tumors while acts as a tumor promoter with Grade 3 tumor." (PMID 33193750, 2020). "By contrast, genetic depletion and pharmacological inactivation of SIRT2 in BLBC cells reversed Slug stabilization and, thus, abrogated relevant pathological features of BLBC and inhibited tumor growth." (PMID 33014852, 2020). "However, it is still under debate whether SIRT2 is an oncogene or a tumor suppressor." (PMID 33207824, 2020). "Recently, several studies have highlighted the critical roles of SIRT2 in maintaining genome stability, suggesting that this SIRT mainly functions as a tumor suppressor." (PMID 31572453, 2019). "The deletion of SIRT2 and SIRT3 stimulated HIF-1α expression and activity, thereby promoting Glut1 expression, glucose uptake and tumor growth." (PMID 31849939, 2019). "SIRT2 is selective for deacetylation of tubulin and contributes to HIF1-α to modulate hypoxia-dependent responses in tumor cells." (PMID 28503576, 2017). "We analyzed the levels of SIRT2 and Skp2 in age-controlled 28 NSCLC specimens, compared to paired adjacent non-tumor lung tissue (NT)." (PMID 26942878, 2016). "We found that the levels of SIRT2 significantly decreased, while the levels of Skp2 significantly increased in NSCLC specimens, compared to the paired non-tumor lung tissue." (PMID 26942878, 2016).
tumor (continued). "Up-regulation of SIRT2 in primary HCC tumors were significantly correlated with the presence of microscopic vascular invasion, a more advanced tumor stage, and shorter overall survival." (PMID 26942878, 2016). "Among the changes driving this benign vs. tumor separation, we observed the downregulation of HDAC3 and Sirt2 as reported." (PMID 27863398, 2016). "In tumor cells, SIRT1 appeared predominantly in the nucleus of the cells whereas SIRT2 was located mainly in the cytoplasm." (PMID 25915617, 2015). "In the present study we have also shown that SIRT2 protein levels are upregulated in NSCLC cell lines and lung tumor cells, when compared with non-tumor cell lines and tissues, respectively." (PMID 25915617, 2015). "While the SIRT2 and SIRT6 actually appear to be tumor suppressors, the most frequently studied subform SIRT1 seems to conditionally operate either as a tumor suppressor or as cancer promoting factor." (PMID 25310649, 2014). "Some sirtuins, such as SIRT2 and SIRT6, seem to function as tumor suppressors, but others, such as SIRT1, are apparently bifunctional, operating as both tumor suppressors and oncogenic factors, depending on cellular context and study conditions." (PMID 25486244, 2014). "In addition to SIRT2, HDAC10 can also reduce G6PD transcription by inhibiting the expression of the histone acetylation, decreasing lung cancer cell proliferation and tumour growth." (PMID 39778006, 2025). "By contrast, SIRT2 and SIRT4 support cytotoxic anti-tumor immunity." (PMID 41425553, 2025). "Furthermore, SIRT2 inhibition induces apoptosis in ATRT cells and, in orthotopic xenograft models, decreases tumor growth and prolongs survival." (PMID 40710366, 2025). "The results suggest the two-edged nature of sirtuins: whereas certain isoforms (e.g., SIRT5) defend malignant cells, thereby undermining therapy, others, such as SIRT2, are involved in tissue-specific protection without promoting tumor survival." (PMID 41425553, 2025). "Inhibiting SIRT2 with selective compounds, such as NPD11033, could reduce tumor cell proliferation and disrupt oncogenic signaling." (PMID 39682281, 2024). "Similarly, SIRT2 contributes to tumorigenesis by regulating KRAS acetylation and MYC stability, while influencing the inflammatory responses that shape the pro-tumor microenvironment." (PMID 39682281, 2024). "For example, elevated levels of Sirtuin 2 (SIRT2) in HCC, as opposed to adjacent normal tissues, are associated with more aggressive disease features and poor prognosis, such as advanced tumor stage and larger size, highlighting their roles in HCC progression." (PMID 38997696, 2024). "It has been found that SIRT2 can interact with PKM2 and affect the metabolic reprogramming and proliferation of tumor cells by regulating the interaction between PKM2 and SIRT2, providing new targets and strategies for tumor therapy." (PMID 39004743, 2024). "SJ-106C, while still inhibiting SIRT1and SIRT2, is enriched in the mitochondria to help with SIRT3 inhibition.It is more active against DLBCL than other solid tumor cells and effectivelyinhibits DLBCL xenograft tumor growth." (PMID 39191393, 2024). "Western blot data show that two isoforms of Sirt2 were present in normal liver and tumor homogenates prepared from Sirt2+/+ mice; however, Sirt2 protein was not present in either the normal or disease liver homogenates prepared from Sirt2−/− mice." (PMID 37628798, 2023). "The involvement of three enzymes, VRK1, Tip60/KAT5 and SIRT2, in the regulation of the level of acetylation of H4K16 opens up the possibility of its pharmacological manipulation by their combination, to promote the elimination of tumor cells." (PMID 36902348, 2023). "Furthermore, we demonstrated that the combination of elesclomol and SIRT2 inhibitor AGK2 is a promising therapeutic strategy, and tackles the research bottleneck of cuproptosis on tumor therapy." (PMID 37863889, 2023).
tumor (continued). "To determine whether SIRT2 and relative acetyl-K98 FGL1 levels correlated with HCC progression, we analyzed the clinical data on tumor stages and IHC staining results." (PMID 37115693, 2023). "Again, we observed no change in the overall incidence of spontaneous tumours in SIRT2‐Tg mice, including no change in the frequency of liver tumours." (PMID 38009412, 2023). "Our results based on the clinical-pathological characteristics of patients with ccRCC showed that the expression of SIRT2, SIRT3, SIRT6, and SIRT7 was increased in tumor-stage 1-4 subgroups, SIRT1 was increased in tumor-stage 1, and the expression of SIRT4 and SIRT5was decreased." (PMID 37096064, 2023). "This implicates Sirt2’s involvement in HCC glucose metabolism, potentially shifting focus away from the promotion of MYC stability to the Warburg effect as the major mechanism to explain the tumor phenotype." (PMID 37628798, 2023). "Since FGL1 is a newly identified immune checkpoint ligand and inhibition of SIRT2 by AGK2 could decrease FGL1 levels in HCC cells, we then determined whether pretreatment of tumor cells with AGK2 would affect T cell activity." (PMID 37115693, 2023). "However, there is quite a consensus in the literature that HDAC4, HDAC7, HDAC9, SIRT2, and SIRT7 are upregulated in GC and seem to be pro-tumor factors, whereas SIRT4, SIRT5, and SIRT6, which are downregulated, seem to have a tumor suppressor function." (PMID 36358890, 2022). "Furthermore, in many other tumour cell types, SIRT2 can deacetylate ACLY and reduce its stability, thereby inhibiting tumour cell proliferation." (PMID 36101744, 2022). "Antibody-mediated depletion of NK cells increased tumor progression in WT mice, but not Sirt2-KI mice, further supporting the integral role of SIRT2." (PMID 34155309, 2021). "Despite a decrease in the number of tumor-infiltrating NK cells, flow cytometry of bone marrow aspirates indicate an increase in NK cells in Sirt2-KI mice compared to WT mice (data not shown)." (PMID 34155309, 2021). "Because these experiments were conducted in mice not bearing tumors, we propose that systemic SIRT2 overexpression suppresses function of NK cells independent of tumor cells." (PMID 34155309, 2021). "We aimed to determine the effect of radiotherapy on SIRT1 and SIRT2, which have not been yet been clarified as a tumor suppressor or promoter." (PMID 33705642, 2021). "Sirtuin 2 (SIRT2) is a class III NAD+-dependent deacetylase, which regulates a broad range of biological functions, including aging, metabolism, differentiation, genome maintenance, and tumor suppression." (PMID 33916219, 2021). "The target of this study was to find the consequence of radiotherapy on soluble SIRT1 and SIRT2 proteins, which have not been yet clarified as a tumor suppressor or promoter molecule." (PMID 33705642, 2021). "While SIRT2 has been identified as a tumor suppressor, these studies might help explain the novel mechanism by which HRD1 regulates tumorigenesis through SIRT2." (PMID 31932479, 2020). "Moreover, we collected twenty pairs of tumor and normal liver tissues from HCC male patients, and found that expression levels of SIRT1 (p = 0.002), SIRT2 (p = 0.01), and SIRT4 (p = 0.045) were significantly up-regulated in tumor tissues." (PMID 33093847, 2020). "Additionally, we also performed IHC staining of the tissue sections and observed significantly low levels of both SIRT2 and TFEB levels in the NSCLC tumor tissues." (PMID 33344455, 2020). "Reduced expression of SIRT2 upregulated cyclin-dependent kinase 4 (CDK4) expression, which eventually accelerated cell proliferation, migration, and invasion, indicating that SIRT2 plays a tumor-suppressor role in OC." (PMID 31572453, 2019). "Elevated levels of Sirt2 in tumor tissues were correlated with poor outcomes for NSCLC patients, suggesting that Sirt2, as the RRM2 deacetylase, could be a potential prognostic biomarker for NSCLC." (PMID 31324785, 2019).
tumor (continued). "Negative SIRT2 protein expression was found in primary tumor samples, though this protein expressed in samples from CRC metastasis." (PMID 28514749, 2017). "After dissociation from sirtuin-2 (SIRT2), a NAD+-dependent histone deacetylase, cytosolic FoxO1 is acetylated allowing its binding to ATG7, which directs the autophagic process towards cell death of tumor cells." (PMID 30563957, 2017). "This is not unexpected because SIRT2 is known to exert tumor-promoting functions by deacetylating various targets." (PMID 29239724, 2017). "The results from this study may partially explain our findings here, in which SIRT2/Skp2/p27 controls NSCLC cell growth, in which SIRT2 appears to be a tumor suppressor and Skp2 appears to be an oncogene." (PMID 26942878, 2016). "In animal models, SIRT2 inhibition resulted in decreased oncogenic markers and an increase in neuronal differentiation markers, suggesting that targeting SIRT2 may promote differentiation in ATRT cells, potentially leading to less aggressive tumor behavior." (PMID 40710366, 2025). "SIRT2 protects neurons by enhancing nucleotide excision repair without affecting tumor response." (PMID 41425553, 2025). "In addition to lifespan, we show no impact of SIRT2 overexpression on age‐related parameters of health, including tumour incidence, glucose homeostasis, mitochondrial function, motor coordination, bone health or sperm function." (PMID 38009412, 2023). "Furthermore, quantification of IHC staining of tumor tissues demonstrated that FGL1 protein levels were positively correlated with SIRT2 expression levels, while the levels of relative acetyl-K98 FGL1 were negatively correlated with SIRT2 expression levels." (PMID 37115693, 2023). "Furthermore, there are higher levels of HBc expression in the biopsied tumor than in the adjacent non-tumor liver tissues, which emphasizes the fact that Sirt2 and HBV together play a role in HBV replication." (PMID 38239506, 2023). "Furthermore, SIRT2 overexpression reduced the organoid formation capacity and blocked the activity induced by LIFR overexpression, which is consistent with the reported tumour suppressor role of SIRT233 and SIRT2‐mediated effects on LIFR function." (PMID 35172032, 2022). "The significant decrease in tumor progression observed in WT, but not Sirt2-KI, mice following NK cell inhibition further supports our hypothesis that NK cells are important in SIRT2-mediated tumor progression." (PMID 34155309, 2021). "Loss of SIRT2 in mouse embryonic fibroblasts (MEFs) resulted in stabilized APC substrates, centrosome amplification, and aneuploidy, with mice lacking SIRT2 experiencing increased tumor development." (PMID 32805721, 2020). "In addition, the weight of the tumours from the mice injected with ShNC SW480 cells was significantly greater than that of the tumours from the mice injected with ShSIRT2 SW480 cells, suggesting that SIRT2 is involved in CRC development." (PMID 30584257, 2018). "Likewise, the tumor-suppressor sirtuin gene SIRT2 was shown to promote APC/C-Cdh1 function through acetylation of Cdh1, and again may explain tumor-suppresive effects of indirect APC/C-Cdh1 inactivation." (PMID 26650195, 2016). "Mechanistically, KRAS K147 is identified as a novel SIRT2-specific deacetylation target by mass spectrometry, whereas its acetylation status directly regulates KRAS activity, ultimately exerting an impact on cellular behavior as revealed by cell proliferation, colony formation, and tumor growth." (PMID 27637077, 2016). "Notably, the positive expression of SIRT2 was mainly located in the cytomembrane and cytoplasm rather than in the nucleus of the tumor specimen with high Fn14 expression compared to those with low Fn14 expression, followed by the down‐regulation of Slug expression in the cells." (PMID 40344622, 2025).